U6 (U6 spliceosomal RNA )
Synonyms: LOC124904687
Gene: Small nuclear RNA gene on chromosome 1 (180,758,722 to 180,758,817, forward strand). Ensembl gene ENSG00000283575.
Gene Ontology:
Molecular function: U4 snRNA binding
Biological process: formation of quadruple SL/U4/U5/U6 snRNP; spliceosomal tri-snRNP complex assembly
Cellular component: U4/U6 x U5 tri-snRNP complex; U6 snRNP
Homologues: Orthologues: zebrafish U6 (97% identical), chimpanzee U6 (96% identical), zebrafish U6 (96% identical), macaque U6 (95% identical), rat LOC120100175 (85% identical). Paralogues in human: RNU6-1 (98% identical), RNU6-12P (98% identical), RNU6-13P (98% identical), RNU6-17P (98% identical), RNU6-18P (98% identical), RNU6-2 (98% identical), RNU6-32P (98% identical), RNU6-3P (98% identical), RNU6-4P (98% identical), RNU6-5P (98% identical), RNU6-6P (98% identical), RNU6-9 (98% identical), and 1284 more.